STING1 (stimulator of interferon response cGAMP interactor 1)
Diseases named in the same sentence as STING1 in open-access papers (continued):
Sharing a sentence is not in itself a finding about the gene and the disease.
pancreatic cancer (95 papers, 2018 to 2026). "Two studies on pancreatic cancer cells have linked DNA damage, STING1 activation, and autophagy-dependent ferroptosis." (PMID 34078874, 2021). "In addition, an animal study also demonstrated that loss of GPX4 in mice with high iron diet and pancreatic cancer accelerated the development of pancreatic ductal adenocarcinoma mediated by Kras mutations through STING1/TMEM173 pathway." (PMID 36387147, 2022). "Moreover, mitochondrial or genomic DNA stress activates STING1-dependent autophagy in pancreatic cancer cells, which may cause lipid peroxidation-mediated ferroptosis." (PMID 34078874, 2021). "In contrast, deletion of the STING1 or MFN1/2 genes reduced the sensitivity of pancreatic cancer cells to ferroptosis." (PMID 37324946, 2023). "In human pancreatic cancer cells, it has been observed that the endoplasmic reticulum protein stimulator of interferon genes (STING1) accumulates in mitochondria and interacts with the mitochondrial outer membrane protein mitofusins (MFN1/2)." (PMID 38155662, 2023). "Specifically, they found that the ER protein STING1 (also known as STING or TMEM173) promoted ferroptosis in human pancreatic cancer cell lines by increasing mitochondrial fusion protein MFN1/2-dependent mitochondrial fusion." (PMID 37324946, 2023). "Of note, one previous study have suggested that STING1 promotes ferroptosis through MFN1/2-dependent mitochondrial fusion in pancreatic cancer cells." (PMID 35697672, 2022). "Here, we show that the ER protein STING1 (also known as STING or TMEM173) promotes ferroptosis in human pancreatic cancer cell lines by increasing MFN1/2-dependent mitochondrial fusion, but not mitophagy-mediated mitochondrial removal." (PMID 34195205, 2021). "In the context of human pancreatic cancer cells, intriguing insights into the promotion of ferroptosis have emerged, particularly involving the endoplasmic reticulum protein stimulator of interferon genes (STING1)." (PMID 38540171, 2024). "Furthermore, 8-hydroxy-2′-deoxyguanosine (8-OHG) functions as a damage-associated molecular pattern (DAMP) during ferroptotic cell death to trigger STING1-dependent macrophage polarization, supporting pancreatic cancer initiation and progression." (PMID 34708125, 2021). "The study found that the antiviral drug zalcitabine induces mtDNA stress, activates the STING1/TMEM173-mediated DNA sensing pathway, and suppresses the growth of pancreatic cancer cells by inducing autophagy-dependent ferroptosis." (PMID 40733146, 2025). "Studies employing both in vitro models and xenografted mouse experiments have highlighted the pivotal role of STING1 and MFN1/2 genes in regulating the sensitivity of pancreatic cancer cells to ferroptosis." (PMID 38540171, 2024). "Erastin induces STING1 to bind MFN1/2 to trigger mitochondrial fusion, leading to lipid peroxidation and subsequent ferroptosis in human pancreatic cancer cell lines." (PMID 39872359, 2022). "Consequently, in vitro or xenograft mouse models show that the genetic depletion of STING1 or MFN1/2 (but not the mitophagy regulator PINK1 or PRKN) reduces the sensitivity of pancreatic cancer cells to ferroptosis." (PMID 34195205, 2021). "In addition to mtDNA, the release of nDNA to cytosol caused by nuclear cathepsin B (CTSB)-mediated genomic DNA damage activates STING1-dependent autophagy and subsequent glutathione peroxidase 4 (GPX4) degradation, leading to ferroptotic cell death in human pancreatic cancer cells." (PMID 34078874, 2021).
COVID-19 (83 papers, 2020 to 2025). A disease caused by infection with severe acute respiratory syndrome coronavirus 2. "The main finding of our study is the significant association between a common functional STING1 variant and the risk of severe COVID-19 hospitalization among individuals who are fully vaccinated with a SARS-Cov-2 mRNA vaccine." (PMID 40868819, 2025). "In conclusion, we reported a significant association of common STING1 SNPs/haplotypes with the risk of hospitalization due to COVID-19 among individuals who were fully vaccinated." (PMID 40868819, 2025). "Based on the reported evidence that implicated the STING pathway in the pathogenesis of COVID-19 and the antiviral response after vaccination, we hypothesized that common functional STING1 variants could be associated with the risk of developing severe COVID-19." (PMID 40868819, 2025).
Obesity (83 papers, 2018 to 2026). Accumulation of substantial excess body fat. "First, like many human studies, our study cannot prove causality, in this case between obesity or STING1 genotype and PPSV23 efficacy." (PMID 32376795, 2020). "Obesity and a WT STING1 genotype are positively associated with efficacy of the 23-valent pneumococcal vaccine in a small cohort of subjects." (PMID 32376795, 2020). "STING1 has been increasingly implicated in inflammatory diseases such as nonalcoholic fatty liver disease, nonalcoholic steatohepatitis, cardiomyopathy, obesity, diabetes, neurodegenerative diseases, aging, and kidney injury, many of which are independent of type I IFNs." (PMID 39291958, 2024). "The levels of IRF7-associated ISG-encoding transcripts, including IFI16, ZBP1 and TMEM173 (STING1), were increased in the adipose tissue of children with obesity, reflecting their elevated IRF7 levels." (PMID 36443525, 2022). "This is the first human study to our knowledge assessing the role of obesity and STING1 genotype in PPSV23 efficacy." (PMID 32376795, 2020). "We assessed the relationship of obesity (primary analysis) and stimulator of interferon genes (STING1) genotype (secondary analysis) on PPSV23 efficacy." (PMID 32376795, 2020). "Recent research revealed that STING1 promotes inflammation in a variety of inflammatory diseases, including nonalcoholic fatty liver disease, nonalcoholic steatohepatitis, kidney injury, neurodegenerative diseases, cardiovascular diseases, obesity, diabetes, and aging." (PMID 39291958, 2024). "Thus, we next asked whether diet-induced obesity affected Sting1 and Cgas levels in the iAT and the eAT." (PMID 37830559, 2023). "Adipose tissue levels of STING1 and CGAS were unaffected by obesity status, albeit plasma STING1 level was moderately increased with increasing BMI z-score." (PMID 37830559, 2023). "The aim of the Result of Obesity on Vaccine Efficacy (ROVE) Study was to utilize a nonrandomized controlled trial to evaluate, in otherwise healthy adults, the effect of obesity (BMI ≥30) versus nonobesity (22 ≤ BMI ≤ 25) on humoral responses to PPSV23 in relation to STING1 genotypes." (PMID 32376795, 2020).
colon carcinoma (79 papers, 2014 to 2026). "Furthermore, knockout of STING1 in HT29 human colon cancer cells significantly attenuated 5-FU plus oxaliplatin-induced levels of P-STING and expression of ISG15 and IFNβ." (PMID 39469633, 2024).
glioma (60 papers, 2016 to 2026). A benign or malignant brain and spinal cord tumor that arises from glial cells (astrocytes, oligodendrocytes, ependymal cells). "We and others have found that in human glioma samples, STING1 is expressed in stromal and immune cells but is uniformly suppressed in neoplastic cells." (PMID 38226619, 2024).
triple-negative breast carcinoma (50 papers, 2020 to 2025). An invasive breast carcinoma which is negative for expression of estrogen receptor (ER), progesterone receptor (PR), and human epidermal growth factor receptor 2 (HER2). "For example, the MYC oncogene in triple-negative breast cancer inhibits STING expression by directly binding to the STING1 enhancer region, leading to tumor immune evasion." (PMID 36297353, 2022).
lung adenocarcinoma (44 papers, 2014 to 2026). A carcinoma that arises from the lung and is characterized by the presence of malignant glandular epithelial cells. "STING (or STING1) activity increases in lung adenocarcinoma cells that re-enter the cell cycle and is dampened by hypermethylation of the STING promoter and enhancer in breakthrough metastases." (PMID 38506114, 2024).
myocardial infarction (43 papers, 2020 to 2026). Gross necrosis of the myocardium, as a result of interruption of the blood supply to the area, as in coronary thrombosis. "Consistent with the pathogenic role of activation of the CGAS-STING1 pathway, deletion of the Mb21d1, Sting1, or Irf3 gene abrogated the induction of the interferon 1 response and improved survival and cardiac remodeling in a mouse model of myocardial infarction." (PMID 40180542, 2025). "STING1, which is a hub molecule in the CDSP pathway, is also an attractive therapeutic target in cardiovascular conditions, including in mouse models of doxorubicin-induced cardiac dysfunction, myocardial infarction, and aortic aneurysm and dissection, among others." (PMID 40180542, 2025).
pulmonary fibrosis (41 papers, 2016 to 2026). Chronic progressive interstitial lung disorder characterized by the replacement of the lung tissue by connective tissue, leading to progressive dyspnea, respiratory failure, or right heart failure. "Genetic modifiers such as SNPs in STING1 itself or other interferon related genes such as IFIH1 could impact disease severity and viral exposure in a STING1 GOF mouse model determined the development of pulmonary fibrosis." (PMID 34867986, 2021).
COPA syndrome (40 papers, 2019 to 2026). "On the other hand, coat protein complex I (COP-I) mediates the retrograde transport of STING1 to the ERGIC from Golgi, while deficiency in COP-I transport causes failure of Golgi-to-ER STING1 retrieval and ligand-independent activation of STING1, thus contributing to COPA syndrome." (PMID 35371032, 2022).
lung disease (40 papers, 2018 to 2025). "Although our understanding of cellular and molecular consequences of STING1 gain-of-function mutations is improving, mechanisms underlying the life-threatening lung disease in SAVI are not yet fully deciphered." (PMID 35159128, 2022).
interstitial lung disease (36 papers, 2016 to 2026). A diverse group of lung diseases that affect the lung parenchyma. "We previously established a SAVI mouse model, by knocking in the disease causing variant N153S into the endogenous murine Sting1 gene (STING ki) resulting in T cell lymphopenia, interstitial lung disease, and systemic autoinflammation." (PMID 40111902, 2025). "Gain-of-function mutations of human STING1 cause SAVI, which is characterized by severe interstitial lung disease, T cell lymphopenia, skin inflammation, and perturbed IFN- and NF-κB-driven signaling." (PMID 40111902, 2025). "Family A consisted of 7 individuals (the father, 3 sons and 3 daughters) carrying the heterozygous variant in STING1 c.463G>A, previously reported as cohort with undiagnosed interstitial lung disease, arthritis, and atopic dermatitis." (PMID 37848930, 2023). "Gain-of-function mutations in STING1 cause the monogenic interferonopathy, SAVI, which presents with early-onset systemic inflammation, cold-induced vasculopathy and/or interstitial lung disease." (PMID 33833757, 2021).
cervical carcinoma (26 papers, 2014 to 2026). A carcinoma arising from either the exocervical squamous epithelium or the endocervical glandular epithelium. "The presence of homozygous variants HAQ/HAQ and R232H/R232H of STING1 was found to correlate with an earlier age at diagnosis and an elevated recurrence rate of cervical cancer, accompanied by poorer survival." (PMID 41142804, 2025). "Researchers have studied the impact of STING1 gene variants, specifically homozygous HAQ/HAQ and R232H/R232H, on cervical cancer outcomes." (PMID 39949780, 2025).
asthma (19 papers, 2020 to 2026). "This hypothesis is further complemented by the M2 polarization profile (APOE, TXN, TGM2, STING1, NAMPT) enriched in this group, a dominant macrophage profile in high Th2-type asthma in humans and one known to activate the Th2 response with downstream eosinophilic infiltration and airway remodeling." (PMID 39594673, 2024).
HIV-1 infection (19 papers, 2016 to 2025). The type species of lentivirus and the etiologic agent of acquired immunodeficiency syndrome (AIDS). "In Class2, molecules like STING1 were enriched in the HIV-1 infection pathway, indicating that co-infection upregulated STING1 to promote the expression of antiviral genes." (PMID 41394852, 2025).
Lewis lung carcinoma (18 papers, 2020 to 2026). "Notably, Sting1−/− Vγ4 γδ T cells exhibited significantly reduced killing capacity against Lewis lung carcinoma (LLC), MC38, and B16 cells, suggesting that endogenous STING is required for γδ T cell‐mediated tumor inhibition in several cancer types." (PMID 39573933, 2025).
squamous cell carcinoma (15 papers, 2017 to 2025). A carcinoma arising from squamous epithelial cells. "DDR-deficient types had lower expressions of STING1 (p = 0.01), CD28 (p = 0.020), HLA-DRB6 (p = 0.014) in adenocarcinoma, lower TNFRSF4 (p = 0.017), and TGFB1 expressions (p = 0.033) in squamous carcinoma, and higher CD40 (p = 0.012) and TNFRSF14 expressions (p = 0.022) in SCLC." (PMID 34604048, 2021).
cardiomyopathy (13 papers, 2021 to 2025). A disease of the heart muscle or myocardium proper. "We determined the activation and the role of the CDSP pathway, also known as the CGAS/STING1 pathway, in the pathogenesis of DSP cardiomyopathy." (PMID 40608429, 2025). "In conclusion, cytosolic self-DNA (nDNA and mtDNA) is increased in cardiomyocytes in DSP cardiomyopathy and activates the CDSP (CGAS/STING1) pathway, which induces the expression of pro-inflammatory genes involved in cardiac dysfunction, cell death, and fibrosis." (PMID 40608429, 2025).
depression (13 papers, 2022 to 2026). "Mitochondrial dysfunction leads to the release of mtDNA and increased ROS, activating the STING1 and NLRP3 inflammasome signaling pathways, promoting the synthesis of inflammatory factors, and consequently triggering inflammation that mediates the occurrence of depression." (PMID 40699781, 2025).
Arthritis (11 papers, 2020 to 2025). Inflammation of a joint. "This study emphasizes that, in the clinical assessment of interstitial pneumonia in children, the possibility of STING1 mutation should be considered, especially in patients with arthritis in addition." (PMID 33014937, 2020).
lymphopenia (11 papers, 2018 to 2025). Reduction in the number of lymphocytes. "Thus, it is likely that the Q293 residue is critical for STING1-mediate lymphopenia." (PMID 39291958, 2024). "Here, we focused on lymphopenia in the SAVI mice that avoids ligand-dependent, non-physiological dosage in STING1-mediated cell death." (PMID 39291958, 2024).
aortic aneurysm (10 papers, 2020 to 2025). A ruptured aneurysm located in the wall of the proximal portion of the descending aorta proceeding from the arch of the aorta. "In a mouse model of aortopathy, systemic inactivation of Sting1 gene, genetically and pharmacologically, afforded partial protective effects against the development of aortic aneurysm and dissection." (PMID 40180542, 2025). "Likewise, the CDSP pathway is activated in a subset of monocytes and macrophages in a mouse model of aortic aneurysm, and deletion of the Sting1 gene in the myeloid cells reduces the development, progression, and rupture of adnominal aortic aneurysm in mice." (PMID 40180542, 2025).
Hypertension (10 papers, 2022 to 2025). The presence of chronic increased pressure in the systemic arterial system. "We also performed a multiple logistic regression comparing ICU vs. non-ICU patients with age, sex, hypertension, dyslipidemia, and the two STING1 variants as covariates." (PMID 40868819, 2025).
pneumonia (6 papers, 2021 to 2026). An acute, acute and chronic, or chronic inflammation focally or diffusely affecting the lung parenchyma, caused by an infection in one or both of the lungs (by bacteria, viruses, fungi, or mycoplasma.). "Pathway readouts supported actions on complementary axes (TLR4-IRAK1, STING1-IFN-β, FPR1-AKT, CASP8, and HDAC2-H3K9ac), providing a mechanistic basis for their collective protection against pneumonia." (PMID 41484909, 2026).
renal carcinoma (6 papers, 2021 to 2025). A carcinoma arising from the epithelium of the renal parenchyma or the renal pelvis. "As a partner of the stimulator of interferon response cGAMP interactor 1, VDAC2 participates in nonclassical innate immune signaling regulated by STING, influencing the growth of renal cancer cells." (PMID 40626007, 2025).
Ataxia (4 papers, 2019 to 2024). Ataxia refers to impaired coordination of voluntary muscle movement. "In Npc1 knockout mice, STING signaling was upregulated and mice were characterized by Purkinje cell (PC) loss and ataxia motor phenotype, while genetic deletion of Sting1 improved PC abundance and ataxia scores." (PMID 39156128, 2024).
endotoxemia (4 papers, 2022 to 2025). "It is noteworthy that during endotoxemia in mice, STING1‐induced apoptosis of CD4+ T cells promotes inflammation‐induced immunosuppression, indicating the potential of STING as a target for treating T cell‐mediated diseases." (PMID 38020710, 2023).
Legionnaires' disease (4 papers, 2018 to 2025). A pneumonia caused by Legionella pneumophila and other Legionella species, which is characterized by fever, cough, progressive respiratory distress, and which is often accompanied by extrapulmonary manifestations. "Moreover, this haplotype (containing 230Ala) was significantly more frequent among patients with Legionnaires’ disease compared to healthy controls, and these STING1 variants have been associated with HIV progression." (PMID 40868819, 2025).
AIDS (3 papers, 2021 to 2024). A syndrome resulting from the acquired deficiency of cellular immunity caused by the human immunodeficiency virus (HIV). "Targeting STING1 to prevent CD4 T cell death might be a valid therapy for AIDS." (PMID 39291958, 2024).
allergic disease (3 papers, 2021 to 2026). An immune response that occurs following re-exposure to an innocuous antigen, and that requires the presence of existing antibodies against that antigen. "To identify these neuromodulators, we exposed (24h) cultured JNC neurons to various allergy driving cytokines, inflammatory lipids, and neurotrophins, and used transcription changes to Npy1r, Sting1, Bdnf, and Il6 as proxies for an AAI-like signature." (PMID 39345572, 2024).
Failure to thrive (3 papers, 2020 to 2022). Failure to thrive (FTT) refers to a child whose physical growth is substantially below the norm. "One of his sisters (patient 4) with ILD, clubbing and failure to thrive (19.9 kg, z-score -2.35, height 115 cm; z-score -2.87) was also diagnosed with the same homozygous PV in STING1." (PMID 36275728, 2022). "The presence of this pattern of signs and symptoms in association with failure to thrive (FTT) and recurrent fever should indicate a STING1 gene study." (PMID 33488593, 2020).
Lysosomal disorder (3 papers, 2022 to 2025). "Lysosomal disorder is associated with increased STING1-mediated immune response, highlighting that lysosomal damage and substance accumulation are the activation signals of the STING1 pathway." (PMID 35371032, 2022).
metastatic colorectal cancer (1 paper, 2025). "Variants in STING1 have been linked to cervical cancer development, while in patients with metastatic colorectal cancer treated with cetuximab-based first-line therapy, IFNB1 rs1051922 correlates with progression-free survival." (PMID 41476984, 2025).
mucositis (1 paper, 2022). Mucositis is inflammation and damage of the mucous membranes lining the mouth and other parts of the gastrointestinal (GI) tract. "The study identified and replicated a locus on chromosome 5 in the STING1 gene to be significantly associated with RT-induced mucositis and meta-analysis confirmed this association." (PMID 35039627, 2022).